IL2 (interleukin 2)
Diseases named in the same sentence as IL2 in open-access papers (continued):
Sharing a sentence is not in itself a finding about the gene and the disease.
eosinophilia (33 papers, 2006 to 2025). "Less common causes of reactive eosinophilia include dialysis, rejection of kidney transplants, IL-2 infusions, toxic oil syndrome, and infections from HIV or human lymphotropic virus-II." (PMID 39301376, 2024). "The first data on cancer patients showing an association between anti-neoplastic treatment and eosinophilia came from a cohort of 20 patients treated with IL-2 and lymphokine-activated killer cells for advanced cancer." (PMID 35563461, 2022). "Previous studies have reported IL-5-induced eosinophilia associated with IL-2/JES6-1 immunocomplex treatment in a murine model of dermatitis as well as in cancer patients that received high- or low-dose IL-2 immunotherapy." (PMID 30930900, 2019). "Immunotherapy using IL-2 has been shown to have moderate success against some tumors and is often associated with “unexpected” but significant eosinophilia, which resulted in assumptions suggesting that eosinophils possess anti-tumor activity, at least in vitro." (PMID 23369060, 2013). "In clinical practice, IL‐2 leads to an increase in IL‐5, a crucial growth, differentiation, and activating factor for eosinophils, which results in eosinophilia." (PMID 38087769, 2024). "No acute side effects were observed with CAR-TIL treatment; however, after IL-2 treatment, gastrointestinal side effects and eosinophilia resolved with treatment discontinuation and re-emerged when reinitiating treatment." (PMID 36765608, 2023). "The eosinophilia observed has been described previously and is likely due to the release of IL-5 and GM-CSF release by IL-2-stimulated CD4-positive lymphocytes." (PMID 36765608, 2023). "In humans, peripheral blood eosinophilia often occurs when immunotherapy with interleukin (IL)-2, IL-4, granulocyte macrophage colony-stimulating factor, or tumor vaccine is performed." (PMID 34170380, 2022). "Neutralization of IL-5 in Cd19CreRosaIL-2 mice prevented the eosinophilia, demonstrating that B cell–specific production of IL-2 initiated an unconventional cellular circuit expanding IL-5–expressing ILC2s and, downstream, eosinophils." (PMID 35699942, 2022). "A study by van Haelst Pisani and colleagues further demonstrated that IL-2 administration was followed by IL-5 production and eosinophilia." (PMID 35563461, 2022). "Patients who receive IL-2 therapy can also exhibit eosinophilia, which evidence suggests is mediated by ILC2 production of IL-556." (PMID 29196657, 2017). "Further phenotypic changes occurred during this IL-2/Jes6-1 treatment, namely an expanded population of IL-5+ ILC2 (Lin− ICOS+), associated eosinophilia and decreased CD11b+ Ly6G− Ly6Chi inflammatory monocytes." (PMID 28589929, 2017). "One of the common pleiotropic effects of high dose IL-2 treatment, eosinophilia, is eliminated at doses of the IL-2 fusion proteins that greatly expand Tregs." (PMID 25457307, 2015). "Following IL-2:anti-IL-2 treatment, airway inflammation and eosinophilia is dampened, and mucus production, AHR to methacholine and parenchymal tissue inflammation are also dramatically reduced." (PMID 24886492, 2014). "According to literature data, IL‐2 may stimulate IL‐5–producing group 2 innate lymphoid cells, which can, in turn, lead to eosinophilia." (PMID 40145321, 2025). "Furthermore, immunotherapy with interleukin (IL)‐2,31, 32 IL‐4,33 granulocyte‐macrophage colony‐stimulating factor, or tumor vaccines often results in peripheral eosinophilia." (PMID 38087769, 2024). "The most prevalent side-effects in the treatment arm were transient flush, mild hypotension, headache (all likely attributed to the HDC component), transient and mild thrombocytopenia, transient eosinophilia, low-grade fever, injection site reactions to IL-2, nausea and dyspepsia." (PMID 38791903, 2024). "Additionally, we observed leukocyte morphological changes, eosinophilia, and increased serum levels of IL-2, IL-4, IL-5, and type I and II interferons." (PMID 37766239, 2023).
eosinophilia (continued). "Previous studies have demonstrated that cytokines such as IL-2, IL-4 could recruit eosinophils and lead to eosinophilia and enhanced eosinophil activation, thereby exert potent anti-tumor immune responses." (PMID 32434481, 2020). "Additionally, a recent report showed that IL-5-producing ILC2s control eosinophilia induced by IL-2 therapy in humans and mice." (PMID 30930900, 2019). "However, a treatment of allergen-sensitized mice with recombinant IL-2 paradoxically increased airway eosinophilia and tissue inflammation in one study." (PMID 25050349, 2014). "Interestingly, while IL-2:anti-IL-2 complex in the airway model was reported to suppress lung eosinophilia, helminth-induced eosinophilia in the MLNCs was unaffected by administration of the complex." (PMID 24185641, 2014). "Therefore our study indicates that precaution should be taken while using IL-2 for immunomodulation, since despite inhibiting, it induces eosinophilia." (PMID 16889674, 2006). "It has also been shown that mice administered IL-2 developed eosinophilia." (PMID 16889674, 2006). "Human eosinophils were reported to express IL-2 receptors; however, in vitro assays suggested that eosinophilia was due to IL-5, rather than direct effects of IL-2." (PMID 35699942, 2022). "Using a mouse model of IL-2–anti-IL-2 antibody complex injection, the Bluestone group demonstrated that ILC2 cells were the primary IL-5–expressing cells arising following these injections, and that ablation of all IL-5+ cells prevented eosinophilia." (PMID 35699942, 2022). "Second, we did not evaluate other molecules that contribute to eosinophilia, such as IL‐2, IL‐3, IL‐5, GM‐CSF, and NKG2D." (PMID 31950647, 2020). "These so-called IL-2 “muteins,” like IL-2 immunocomplexes, may also lead to ILC2 expansion, IL-5 production, and eosinophilia." (PMID 30930900, 2019). "IL-2/JES6-1 immunocomplexes and low-dose IL-2 therapy are also stimulatory for group 2 innate lymphoid cells (ILC2s) that express CD25, which can contribute to IL-5 production and eosinophilia." (PMID 30930900, 2019). "Additionally, IL-5, which is associated with eosinophilia and VLS induced by high-dose IL-2, did not significantly change in response to SAR’245 treatment alone or in combination with pembrolizumab or nivolumab." (PMID 39320047, 2024).
uveitis (32 papers, 2011 to 2025). An inflammatory process affecting a part of or the entire uvea. "Research work indicates that uveitis is strongly associated with inflammatory and immune cytokines, including tumor necrosis factor, interleukin 1 (IL-1), IL-2, IL-6, IL-8, and interferon gamma (IFN-γ)." (PMID 40687721, 2025). "In addition, after confirmation of the IL2/IL21 genetic region influence on uveitis genetic predisposition, more studies would be required in order to reveal the causal variant/s responsible and to clear up the influence of this region on the uveitis etiology." (PMID 23676143, 2013). "The network showed that LXD exerted therapeutic effects upon valuable targets participated in the genesis and development of uveitis, including Notch1, IL-6, IL-2, TNF, and IL-10." (PMID 40918405, 2025). "The presence of cytokines (interferon gamma, IL-2) in ocular tissue obtained from patients with intraocular inflammation (uveitis) has been confirmed." (PMID 35160111, 2022). "Interleukin 2 (IL-2) has been detected in inflamed uveal and retinal tissue, and IL-2 receptor levels are also increased in patients with certain types of uveitis." (PMID 35160111, 2022). "Elevated IL-2 levels have been reported in sera from BD patients with uveitis compared with non-uveitis patients and in a mixed BD cohort with active disease but where only 6/44 patients had uveitis compared with healthy controls." (PMID 35003055, 2021). "The Mann–Whitney U test showed significant differences between IL-2 serum levels of groups entitled “BD with uveitis” and “recovered uveitis BD” (pvalue = 0.002)." (PMID 28468317, 2017). "Results showed that only IL-2 increased in cases of active uveitis, and, after treatment (without any using of biologic agents), it decreased in cases of recovered uveitis BD." (PMID 28468317, 2017). "Daclizumab treatment in endotoxin-induced uveitis reduced Th1 lymphocytes-related cytokines, such as Interleukin-2 and Interferon gamma, by about 60–70% and presented a preventive role in endotoxin-induced oxidative stress." (PMID 24595020, 2014). "In uveitis condition, IL-2 induces the expansion of Th17 cells, which were found to be elevated in uveitis patients." (PMID 23676143, 2013). "Functional studies have revealed that Th17 cells contribute to uveitis through expanded IL-2, while IL-21 was highly expressed and promoted the differentiation of Th17 cells in both in vitro and in vivo studies." (PMID 22876110, 2012). "Taken together, these studies indicate that IL2, IL21, and IL27 play important roles in the development of uveitis, predicting an association of these two SNPs (rs4505848 and rs4788084) with AU." (PMID 22065918, 2011). "Functional studies have revealed that Th17 cells contribute to uveitis through expanded IL-2, meanwhile IL-21 was highly expressed and promoted the differentiation of Th17 cells both in vitro and in vivo studies." (PMID 22065918, 2011). "The IFN-γ and IL-2 levels in the aqueous humour and serum were greater in samples from patients with uveitis than in those from controls, but the IFN-γ levels in the peripheral blood (39.26 ± 34.11 pg/ml) were greater than those in the aqueous humour (13.86 ± 1.68 pg/ml) among these patients." (PMID 40000515, 2025). "IL-2 may mediate the development of uveitis by stimulating the proliferation of Th17 cells and the differentiation of Th1 cells." (PMID 33816637, 2021). "We may summarize that the upregulation of inflammatory cytokines plays an important role in the pathophysiology of uveitis, mainly IL-6, as well as IL-1β, IL-2, INFγ, TNFα, IL-10, and GM-CSF." (PMID 33921773, 2021). "IL-2 probably contributes to the ocular immune responses, peculiarly in the presence of activated T cells in the uvea and peripheral blood of patients with active uveitis and its crucial role in T cell-mediated immunity." (PMID 34863132, 2021). "The authors have thus concluded that IL-2 may be a new target for treatment of refractory BD uveitis." (PMID 30154798, 2018).
uveitis (continued). "The significant elevation of IL-2 in patients with uveitis indicates that it is likely the main role in the pathophysiology of BD uveitis and may be considered as a new target for refractory disease therapies." (PMID 28468317, 2017). "Interestingly, on the one hand IL-2 inhibits the differentiation of Th17 cells, although on the other hand it induces the expansion of Th17 cells once developed that mediate uveitis." (PMID 23676143, 2013). "Therefore, the use of anti-IL-2 therapy in various forms of uveitis might be a promising treatment option." (PMID 22876110, 2012). "The production of inflammatory cytokines induced by HTLV-1-infected T cells, such as IL-1α, IL-2, IL-3, IL-8, IL-10, TFN-α and GM-CSF, produces an intraocular inflammatory environment in patients with uveitis." (PMID 37605273, 2023). "The levels of EGF, fractalkine, IL1-β, IL-17A, IL-1RA, IL-2, IL-23, IL-8, IP-10, TNF-α and IL-6 in patients with uveitis in their active phase were independent to their counterpart levels in plasma, the difference being statistically significant (p < 0.05)." (PMID 36498608, 2022). "As is the case with steroids, antibiotics, or biologics including anti-INF-γ, anti-IL-2 (daclizumab), TNF-α (etanercept, infliximab, adalimumab), IL-12/IL-23 antagonist (ustekinumab) that have also been used in uveitis, these drugs are for short-term use." (PMID 34603297, 2021). "When comparing uveitis entities, the B27+ AAU group showed significantly increased levels of IL-2, IL-6, IL-18, IL-22, IL-1β, and interferon (IFN)-γ." (PMID 34783307, 2021). "The ocular fluids from BD patients with active uveitis contained significant amounts of inflammatory cytokines, such as IFN-γ, IL-2, TNF-α, IL-6, and IL-17." (PMID 22546542, 2012). "The levels of interleukin 2 (IL-2), interleukin 21 (IL-21), and their receptors were found to be upregulated in both experimental autoimmune uveitis (EAU) animals and in uveitis patients." (PMID 22876110, 2012). "The levels of IL2, IL21, and their receptors were found to be significantly elevated in uveitis patients and animal uveitis models." (PMID 22876110, 2012). "Ocular fluids from active uveitis patients who have BD contained significant amounts of inflammatory cytokines such as IFN-γ, IL-2, TNF-α, IL-6, and IL-17, while ocular fluids from infliximab patients did not contain any inflammatory cytokines." (PMID 22546542, 2012). "Studies have shown that the levels of interleukin 2 (IL-2), interleukin 21 (IL-21) and their receptors were upregulated in both experimental autoimmune uveitis (EAU) animals and in uveitis patients." (PMID 22065918, 2011). "Results of data analysis of IL-2 serum levels in the three groups were as follows: BD without uveitis (mean = 537, SD = 568), BD with uveitis (mean = 1184, SD = 1658), and recovered uveitis BD (mean = 506, SD = 491), respectively." (PMID 28468317, 2017). "Vitreous samples from 60 patients with PIOL (n = 17), OCL (n = 9), uveitis (n = 23) or retinal detachment (RD) without hemorrhage (n = 11) were analyzed for IL-2, IL-4, IL-6, IL-10, IFNγ, and TNFα concentrations by CBA." (PMID 23405064, 2013). "Levels of IL2, IL21, and their receptors were significantly increased during uveitis in patients and animal models and they may participate in the regulation of T-cell responses." (PMID 22065918, 2011). "It has been reported that IL-2 and retinoic acid (RA) can promote the induction of antigen-specific type 1 Treg (Tr1) cells in EAU, suggesting that IL-2 might be a promising agent for the treatment of uveitis." (PMID 33816637, 2021). "The increase of IL-2 in BD patients with active uveitis and the decrease in BD cases without uveitis and recovered BD uveitis could be evidence for the role of CD4+T helper cells in patients with uveitis." (PMID 28468317, 2017).
uveitis (continued). "Discussion: Significant elevation of IL-2 in patients with uveitis (in comparison with recovered or without uveitis cases) demonstrates that it may be one of the main proteins that enroll in the pathophysiology of BD uveitis and may be considered as a new target for refractory disease therapies." (PMID 28468317, 2017). "The levels of EGF, fractalkine, IL1-β, IL-17A, IL-1RA, IL-2, IL-23, IL-8, IP-10, TNF-α and IL-6 in patients with uveitis in their active phase were independent of their counterpart levels in plasma, the difference being statistically significant (p < 0.05)." (PMID 36498608, 2022).
Crohn disease (30 papers, 2010 to 2025). A gastrointestinal disorder characterized by chronic inflammation involving all layers of the intestinal wall, noncaseating granulomas affecting the intestinal wall and regional lymph nodes, and transmural fibrosis. "Low-dose IL-2 is expected to offer a promising therapy for diseases associated with intestinal barrier damage such as UC and Crohn's disease." (PMID 32308767, 2020). "Our results are important to consider for understanding off-target impacts of IL-2C regimes in experimental models and for considering how IL-2 may contribute to the etiology or severity of gut-associated conditions such as Crohn’s Disease." (PMID 32728053, 2020). "In addition, IL-2-producing ILC3s are important for the oral tolerance of dietary antigens in the small intestine, while the decrease of IL-2 production from ILC3s is associated with lower Tregs frequencies in Crohn’s disease." (PMID 35844606, 2022). "PTPN2 is one of several genes encoding proteins involved in the IL-2 signaling pathway, including IL2 itself, which associate with T1D RA, and Crohn’s disease in genome wide association (GWAS) studies." (PMID 36399073, 2023). "Additional evidence suggests that individuals who had intestinal inflammation due to Crohn’s disease had a shift from IL-22 producing ILC3 to CD127 + IFN-γ producing ILC1 under the influence of IL-2 and IL-12." (PMID 34445953, 2021). "Healthy-derived ASCs were unable to activate CD4+ T-lymphocytes, whereas Crohn’s disease-derived ASCs increased CD4+ T-cells proliferation by approximately 3%, which was associated with an increase in IL-2 (3.325 pg/mL vs. 9.615 pg/mL, respectively), a cytokine released by activated CD4+ T-cells." (PMID 33924264, 2021). "Previous analyses of Crohn's disease describe an enrichment of pathways involved in calcium signaling, Transcription/ChREBP regulation, Immune response (IL2, IL3, IFN alpha/beta, antigen presentation), lipid metabolism, and the developmental role of CDK5 in neuronal development." (PMID 20584322, 2010). "Fecal cytokine analysis has identified IL-2 and IFN-γ in norovirus-induced diarrhea and TNF-α in Crohn’s disease as potential biomarkers." (PMID 40458399, 2025). "Generally, Crohn’s disease has a T helper 1 (Th1) cytokine profile where the Th1 cells produce pro-inflammatory cytokines such as interferon-γ (IFN-γ), interleukin 2 (IL-2) and tumor necrosis factor α (TNF-α)." (PMID 35766160, 2022). "We further demonstrated that GSK2256294, a clinical EPHX2i, reduced the production of IL2, IL12p70, IL10 and TNFα in both ulcerative colitis and Crohn's disease patient-derived explant cultures." (PMID 31002701, 2019). "In a Crohn’s disease model, CXCL10 blockade reduces serum IL-12p40, IL-2, IFN-γ, IL-1α, IL-1β, and TNF-α." (PMID 29910805, 2018). "Consistent with a mouse model, patients with Crohn’s disease have diminished IL-2+ ILC3s in the intestine but no remarkable difference in other IL-2-producing cells compared to healthy controls." (PMID 37063879, 2023). "Moreover, the mucosa of patients with established Crohn's disease are dominated by CD4+ T lymphocytes, which are distinguished by their capacity for producing interferon-γ (IFN-γ) and interleukin-2 (IL-2)." (PMID 24340073, 2013).